ICMT-DT (ICMT divergent transcript)
Synonyms: MGC40168; C1orf211; LINC00337; NCRNA00337
Gene: Long non-coding RNA gene on chromosome 1 (6,234,692 to 6,239,448, forward strand). Ensembl gene ENSG00000225077.
Diseases named in the same sentence as ICMT-DT in open-access papers:
ICMT-DT is named in the same sentence as 10 diseases in open-access papers, as found by Europe PMC text mining. Sharing a sentence is not in itself a finding about the gene and the disease.
ICMT-DT shares sentences with these, for which no sentence is quoted: tumor (7 papers); breast cancer (3); cancer (2); esophageal squamous cell carcinoma (2); fibroids (2); gastric cancer (2); lung adenocarcinoma (2); lung carcinoma (2); pancreatic ductal adenocarcinoma (2); cervical cancer (1).